EPCAM (epithelial cell adhesion molecule)
Diseases named in the same sentence as EPCAM in open-access papers (continued):
Sharing a sentence is not in itself a finding about the gene and the disease.
cancer (continued). "The mechanism of EpCAM induced proliferation in cancer cells has been shown to involve regulated intracellular membrane proteolysis (RIP)." (PMID 29464122, 2017). "The mouse ascites contained EpCAM-positive cancer cells as demonstrated by IMS, also confirmed by strong EpCAM staining on western blots." (PMID 28977905, 2017). "The on-chip process started from the incubation between epithelial-enrich immunomagnetic beads (EpiEnrich beads, anti-EpCAM antibodies coated beads) and the cell pellets to capture the target cancer cells in bile." (PMID 28652576, 2017). "The characterization of both CTC size and EpCAM expression levels from cancer patients clearly shows the heterogeneity of the CTCs and unequivocally demonstrates the advantages of a negative selection based clinical CTC technology." (PMID 28883519, 2017). "Further analyses revealed increased migration and invasion of EpCAM-negative/low cancer cells, which was however contradictory to reports on increased migration and invasion in the presence of EpCAM." (PMID 27683128, 2017). "With the other arm, catumaxomab and blinatumomab bind cancer cells expressing epithelial cell adhesion molecule (EpCAM) or cluster of differentiation 19 (CD19), respectively." (PMID 29379493, 2017). "A contribution of EpCAM to “cancer stemness” is further conceivable given its capacity to stimulate pluripotency of embryonic stem cells." (PMID 27683128, 2017). "E-cadherin is a normal epithelial cell adhesion molecule and is considered as a cancer metastasis suppressor." (PMID 29234409, 2017). "The present study, to our knowledge, is the first to report the existence of EpCAM+ cancer stem‐like cells in advanced cirrhotic patients." (PMID 28176469, 2017). "In CD133−/EpCAM+ cells significantly altered DNA regions contained factors known to be involved in cancer such as VEGFB and MIR192." (PMID 28347289, 2017). "This trifunctional antibody has the ability to bind EpCAM-expressing cancer cells as well as cytotoxic T-cells via the CD3 receptor." (PMID 28531111, 2017). "EpCAM positive cells were readily identified in blood samples from patients with cancers derived from several distinct epithelial sources." (PMID 29137267, 2017). "EpCAM has long been widely used to detect and enumerate CTCs, but EpCAM expression is down-regulated if the cancer cells have undergone EMT because it is an epithelial marker." (PMID 29113414, 2017). "Doing so detected CTCs in nearly all the cancer patients—a substantial improvement over testing for EpCAM CTCs alone." (PMID 29657983, 2017). "Simultaneous binding of CD3 and EpCAM or CD19 bring in the close proximity cancer cells with T-cells leading to a specific and highly efficacious killing process of the cancer cells." (PMID 29379493, 2017). "EpCAM-positive cancer cells were captured by an antibody that exists on the functional domain of the CellCollector." (PMID 28842574, 2017). "With developments in molecular biological and immunological techniques, EpCAM-targeted cancer treatment therapy has been constantly updated." (PMID 28403178, 2017). "In the great majority of cancer entities, EpCAM overexpression strongly correlates with worse overall survival rate and poor prognosis, and distinguishes patients at high risk for recurrence." (PMID 28531111, 2017). "In 2009, catumaxomab, a triomab co-targeting EpCAM/CD3, was approved for the intraperitoneal treatment of malignant ascites in patients with EpCAM-positive cancers." (PMID 28931402, 2017). "As a first step in identifying and characterizing CTCs in cancer patients we examined blood cells using immunofluorescence with antibodies against EpCAM, a widely used biomarker for cancers of the epithelial lineage." (PMID 29137267, 2017). "IHC score was collected, recorded, and analyzed for distribution, intensity, and percentage of cancer cells stained for EpCAM." (PMID 29202724, 2017).
cancer (continued). "Epithelial cell adhesion molecule is a cell-surface glycoprotein that is over-expressed in various cancers of epithelial origin." (PMID 29202724, 2017). "We sought to develop a CART cell technology to target EpCAM-positive cancers for patients with end-stage peritoneal metastasis who otherwise have no viable treatment options." (PMID 28088790, 2017). "When EpCAM is expressed on the surface of cancer cells, it can be cleaved by a variety of proteases, including trypsin, at the position Arginine80/Arginine81." (PMID 29202724, 2017). "To further analyze the molecular mechanisms underlying chemoresistance in a subpopulation of EpCAM-positive cancer cells, we investigated the effect of EpCAM expression on platinum anticancer drug-induced apoptosis." (PMID 28574829, 2017). "EpCAM is expressed on a subset of normal epithelia and overexpressed on malignant cells derived from a variety of malignant tumors; furthermore, EpCAM was particularly over-expressed on some populations of CSCs." (PMID 28930164, 2017). "In assessing potential ‘cross-talk' between proximal microwells, we did not observe detectable protein in empty microwells proximal to cancer marker-positive cell-laden microwells, with the exception of low-level EpCAM background." (PMID 28332571, 2017). "According to the results, the development and invasiveness of HCC is described by a subset of EpCAM+ cells to open a new avenue for eradication of HCC cancer cell by targeting beta-catenin or Wnt signaling components, like EpCAM." (PMID 28819584, 2017). "The HA-SMA-CDF nanomicells were shown to elicit stronger anti-cancer responses against CD44+/CD133+/EpCAM+ CSCs compared with CD44-/CD133-/EpCAM- cells." (PMID 28611316, 2017). "This study also presents strong evidence that EpCAM expression is a suitable biomarker for cancer and precancerous lesions of the uterine cervix." (PMID 29202724, 2017). "Generally, the number of CTCs is lower in HCC patients than in other cancer patients, when the EpCAM-based CTC detection system is used to measure the number of CTCs9–11,36." (PMID 29038587, 2017). "Ultimately, EpCAM was recognized as a membrane protein that is strongly overexpressed in cancer stem cells of all major carcinoma entities." (PMID 27683128, 2017). "In 2009, the European Medicines Agency approved the use of the trifunctional bispecific antibody catumaxomab, which binds to EpCAM and enhances the immunological response against EpCAM-positive cancer cells." (PMID 28574829, 2017). "Epithelial cell adhesion molecule (EpCAM) is considered as a cancer stem cell (CSC) biomarker and one of the most promising targets for aptamer selection against CSCs." (PMID 29245156, 2017). "EpCAM was overexpressed in epithelial progenitor cells, carcinoma cells, and cancer triggering cells." (PMID 29464122, 2017). "This group constructed an AsiC composed of an EpCAM binding aptamer and a siRNA targeting EpCAM mRNA, thereby creating a feedback loop in which the inhibition in the cancer cells was directly proportional to EpCAM expression." (PMID 28792479, 2017). "EpCAM-positive/high cancer cells were characterized by increased tumorigenicity, enhanced proliferation and diminished sensitivity towards growth factor deprivation." (PMID 27683128, 2017). "Additionally, EpCAM consistingof a 289-amino-acid-long extracellular domaincalled EpEX and a 26-amino-acidshort intracellular domain called EpICD, and Fong’s study found that the loss ofmembranous EpICDexpression is a common event inhuman epithelial carcinomas." (PMID 28403178, 2017).
cancer (continued). "EpCAM displayed epithelial specificity as well as frequent and high expression in numerous carcinomas." (PMID 27683128, 2017). "Since most carcinomas express epithelial markers, epithelial cell adhesion molecule (EpCAM) is most commonly used in antibody-based positive selection with commercial technologies." (PMID 28626429, 2017). "EpCAM is a 40-kDa type I transmembrane glycoprotein that is known to be highly expressed in epithelial carcinomas and serves as a prognostic factor." (PMID 28403178, 2017). "Cytotoxicity of T cells in the presence of the EpCAM BiTE was measured in six different carcinoma cell lines, with greatest cytotoxicity observed in DLD and A431, and least in A549 and PC3." (PMID 28634161, 2017). "Immunohistochemical studies revealed that EpCAM is overexpressed on various carcinoma cells in breast, prostate, ovarian, lung, colon, renal, and gastric cancer." (PMID 28820475, 2017). "Other studies showed a strong, circumferential membrane reaction of EpCAM in carcinoma cells of the urinary bladder." (PMID 28820475, 2017). "This work demonstrating the presence of tumoral MPs expressing EpCAM in pleural fluids also opens new directions about the MPs role in cancer progression." (PMID 26689993, 2016). "Among them EpCAM has been historically one of the most famous Ags as a target for therapeutic Abs against cancers and several groups are still trying to develop them although the form of Abs has been changed from a simple mAb." (PMID 27834817, 2016). "This multifunctional structure demonstrated promising therapeutic potential and served as a bio-imaging tool in EpCAM expressing cancer systems in vitro." (PMID 27827876, 2016). "Observations on the dynamic expression of EpCAM on cancer cells have raised the concern of missing relevant CTCs when using exclusively EpCAM-capture for detection." (PMID 27391263, 2016). "The FDA-approved CellSearch (Veridex TM, Raritan, NJ) platform uses immunomagnetic beads coated with antibodies against EpCAM to enrich for EpCAM-expressing cancer cells." (PMID 27013581, 2016). "Using an ELISA test with a detection limit at 1 pg/ml, EpCAM+ MPs were found in 44% (32/71) of cancer patients with a median value of 228 pg/ml." (PMID 26689993, 2016). "The passive mixer facilitates mixing of EpCAM magnetic beads with the CTC‐rich effluent from the spiral sorter so that magnetic beads bind to cancer cells through antibody–antigen complexes." (PMID 27711257, 2016). "The immunotherapeutic catumaxomab targets EpCAM positive cancers and is approved for the treatment of peritoneal carcinomatosis." (PMID 27058902, 2016). "The limitations of EpCAM-based capture methods indicate the urgent need to develop alternative cancer type-specific capture antigens for improved capture of CTCs." (PMID 27494883, 2016). "Based on literature research various cancer markers were considered for the detection of taMPs expressing common cancer antigens as EpCAM and CD147." (PMID 27127176, 2016). "The AsiC was specifically internalized and inhibited target gene expression in EpCAM positive cancer cells and in human cancer biopsy tissues." (PMID 27827876, 2016). "Cells were immunomagnetically separated if they expressed either the epithelial cell surface marker EpCAM, or CD90, a mesenchymal stromal cell marker associated with tumorigenic stem-like cancer cells." (PMID 28721373, 2016). "The findings of a Phase 1 trial in patients with chemotherapy refractory EpCAM positive cancers were recently published." (PMID 27058902, 2016). "Additional cancer stem cell markers such as CD44 or epithelial cell adhesion molecule (EpCAM) have also been the target of PCI treatment, confirming the efficacy of relevant immunotoxins based on saporin." (PMID 25758607, 2016). "By targeting CD133 and EpCAM simultaneously, our TetraKE addresses the polygenetic nature of most cancers and enhances probability to attack cancer at its basal root, the CSC." (PMID 27650544, 2016).
cancer (continued). "The microfluidic CTC capture chip was able to achieve a superior capture yield for both epithelial cell adhesion molecule positive (EpCAM+) and EpCAM- cancer cells in blood samples." (PMID 27501846, 2016). "EpCAM is a well-established CSC target which has diverse roles in cancer cells, such as cell signaling, proliferation, differentiation, and migration." (PMID 27240402, 2016). "The pathological histology of ENM in two examples was found without the histological evidence of lymph nodes structure and the cancer cells highly expressed EpCAM." (PMID 27563811, 2016). "The inadequacy of the EpCAM-based immunomagnetic capture method compared with the size-based filtration method has been reported in several studies for different cancers." (PMID 25862542, 2016). "EpCAM over-expression is correlated with cancer malignancy and with poor survival in breast, ovarian, colon, esophageal squamous cell carcinoma and squamous head and neck carcinoma cells." (PMID 26984381, 2016). "We found that the cancer epithelial cell markers EPCAM and cytokeratin 19 (KRT19) were highly correlated in 79 HCCs (R=0.87)." (PMID 27191501, 2016). "EpCAM is involved in cell signaling, migration, proliferation, cell cycle regulation, and cancer metastasis." (PMID 27421772, 2016). "EpCAM is connected to the Wnt/β-catenin pathways, implying relevance in physiologic and cancer stem-cell (CSC) regulation." (PMID 27650544, 2016). "For example, EPCAM has frequently been investigated as a biomarker for detecting circulating or metastatic carcinoma cells and as a cancer stem cell marker in some malignancies." (PMID 26528695, 2016). "EpCAM, the epithelial cell adhesion molecular, is a 40 kd cell surface glycoprotein identified as a marker for epithelial cancers, as well as a marker for cancer stem cells and hESCs." (PMID 27009809, 2016). "EpCAM overexpression in cancer cells was found to be 100- to 1000-fold higher compared to expression on normal breast cells resulting in 100,000 to 400,000 copies per cell." (PMID 27842504, 2016). "Specifically, with the microfluidic CTC capture device, we were able to achieve capture yields of > 80 % for both EpCAM+ (MCF-7, SUM-149, A549) and EpCAM- (MDA-MB-231) cancer cell lines spiked in whole blood samples." (PMID 27501846, 2016). "In order to evaluate the safety and tolerability of ascending intravenous doses of catumaxomab in patients with chemotherapy refractory EpCAM positive cancers a phase I, open label, dose escalating trial was carried out." (PMID 27058902, 2016). "During EMT cancer cells partially downregulate EpCAM and epithelial features while gradually acquiring mesenchymal characteristics such as vimentin expression." (PMID 27391263, 2016). "Recent data linked EpCAM to WNT/β-catenin signaling, which represents a key pathway in both cancer stem cells and normal adult stem cells and plays an important role in self-renewal and differentiation." (PMID 27240402, 2016). "For example, a theranostic nanoprobe has been developed by combining cancer targeting of a DNA-based EpCAM aptamer with the imaging capability of magnetic iron oxide nanoparticles modified with carboxymethyl cellulose." (PMID 27827876, 2016). "In mammary epithelial cells, SNAI2 is enriched in EpCAM-expressing cells while in some of the pulmonary metastatic high-grade carcinomas, the expression of epithelial marker EpCAM is downregulated and so does the SNAI2 expression." (PMID 27760172, 2016). "Inhibition of EpCAM expression has been shown to result in a dramatic change in phenotype and a decreased proliferation of carcinoma cells." (PMID 26984381, 2016). "The antigen used most often for isolating CTCs is EpCAM (epithelial cell adhesion molecule), an epithelial marker overexpressed in some carcinomas." (PMID 27657044, 2016).
cancer (continued). "The EpCAM molecule is known to be a marker of great therapeutic interest for targeting carcinoma and is overexpressed in a myriad of different carcinoma tissues such as colon, ovary, breast and prostate cancer." (PMID 27650544, 2016). "For example, the CellSearch System by Veridox enumerates those epithelial cell adhesion molecule (EPCAM) expressing carcinoma cells." (PMID 27764803, 2016). "This NK-cell engager binds CD16 on NK-cells, EpCAM, overexpressed on epithelial carcinomas, and CD133, expressed on CSC." (PMID 27240402, 2016). "Epithelial cell adhesion molecule (EpCAM), also known as CD326 and 17-1A antigen, is a transmembrane glycoprotein originally identified as a marker for carcinoma." (PMID 27690012, 2016). "Our study identified metastasis of the four most common carcinomas (prostate, lung, breast and colon) from CTCs, which typically express high levels of EpCAM." (PMID 26695546, 2016). "The original contribution of this work is a self-sustaining TetraKE comprising an anti-CD16 scFv for NK cell engagement, anti-EpCAM scFv for carcinoma recognition, anti-CD133 scFv for CSC recognition, and an IL-15 cross-linker to sustain the NK cell response." (PMID 27650544, 2016). "A recent study demonstrated that the release of EpICD from EpCAM triggers proliferation- and stemness-enhancing signaling in cancer cells." (PMID 26317650, 2015). "The overexpressed proteins including epidermal growth factor receptor, glypicans and epithelial cell adhesion molecule (EpCAM) have widespread roles in numerous cancers, thereby supporting the authenticity of our SILAC screen." (PMID 25630468, 2015). "In positively stained cancer cells, EpCAM was primarily localized on the cell membrane, with occasional diffusion in cytoplasm." (PMID 26698569, 2015). "Actually, EpCAM is the prime epithelial antigen in use to isolate CTCs and to characterize DTCs once they have left the primary cancer." (PMID 25477371, 2015). "Epithelial cell adhesion molecule (EpCAM) is overexpressed in solid tumors and regarded as a putative cancer stem cell marker." (PMID 25576037, 2015). "Inherit absence or down-regulation of EpCAM which associates with EMT and cancer progression as well as metastasis, inevitably result in failure to isolate those “uncapturable” CTCs by means of anti-EpCAM or its derived techniques." (PMID 26718583, 2015). "Most importantly, EMT is more and more recognized to play an important role in metastasis and certain EMT cancer cells will lose EpCAM expression." (PMID 26397728, 2015). "Collectively, our results indicate that the novel anti-EpCAM mAb can potentially be used for cancer-targeted therapy." (PMID 26317650, 2015). "CytoTrack is a novel technology and thus there is a need for more in vitro studies of cells from different cancer types spiked into blood and in vitro studies with EpCAM or CK weak cells to investigate the limits of the two technologies." (PMID 25608842, 2015). "Within the presented study, we aimed to improve CTC enrichment/blood testing in an EpCAM-independent manner providing the opportunity to target multiple epithelial- and/or cancer-related antigens expressed on CTCs simultaneously." (PMID 26695635, 2015). "The role of EpICD in regulating the cancer stem cell markers in RB was elucidated for the first time and our group has already shown the relevance behind EpCAM and mir-17-92 cluster in RB." (PMID 26176230, 2015). "In this study, we generated five mAbs targeting EpCAM, including EpAb2-6, which demonstrated a unique capability to directly induce apoptosis in cancer cells and to inhibit EpICD cleavage." (PMID 26317650, 2015). "Upon dissociation of spheroids on day 5 to identify the proliferating population, we found that the predominant proportion of the proliferating cells in the co-cultures was cancer cells (EpCAM-positive)." (PMID 26053043, 2015).